LINC02702 (long independently transcribed non-coding RNA 2702)
Synonyms: LASER
Gene: Long non-coding RNA gene on chromosome 11 (116,639,422 to 116,658,295, forward strand). Ensembl gene ENSG00000237937.
Diseases named in the same sentence as LINC02702 in open-access papers:
LINC02702 is named in the same sentence as 3 diseases in open-access papers, as found by Europe PMC text mining. Sharing a sentence is not in itself a finding about the gene and the disease.
LINC02702 shares sentences with these, for which no sentence is quoted: atherosclerosis (2 papers); cancer (1); Hypercholesterolemia (1).